GAS6 (growth arrest specific 6)
Diseases named in the same sentence as GAS6 in open-access papers (continued):
Sharing a sentence is not in itself a finding about the gene and the disease.
cancer (continued). "In some cancer types, it could be demonstrated that a higher expression of Gas6 and Axl were associated with poorer survival." (PMID 35760058, 2022). "AXL and its ligand, GAS6, have been implicated in metastasis and tumorigenesis of various cancers." (PMID 34831142, 2021). "GAS6-AXL signaling is associated with cancer cell invasiveness and migration." (PMID 32055714, 2020). "The associations of Gas6 with cancer have been reported in a wide variety of cancers." (PMID 29386018, 2018). "The association of Gas6 with cancer has been summarized thoroughly in this review." (PMID 29386018, 2018). "Furthermore, the AXL ligand growth arrest‐specific gene 6 (GAS6) has recently been linked to cancer drug resistance." (PMID 28675785, 2017). "However, some findings have suggested that Gas6 is associated with the development of resistance to cancer therapies." (PMID 28333143, 2017). "In addition, Gas6 / Axl system linked to multiple types of human cancer." (PMID 32483414, 2020). "Increased Gas6 expression further induces cancer aggressiveness and release of factors that can trigger more Gas6 production, creating a kind of vicious cycle." (PMID 40624025, 2025). "TANs contribute to chemoresistance, with growth arrest-specific protein 6 (Gas6) from neutrophils promoting cancer cell regeneration via the Gas6/AXL pathway." (PMID 40443678, 2025). "Cancer cells are known to stimulate Gas6 production in macrophages to fuel cancer cell proliferation." (PMID 40624025, 2025). "In our study, M2 macrophages were characterized by the presence of anti-inflammatory markers Gas6, Ch25h, and Olfml3, as well as the pro-cancer marker Hpgds." (PMID 41361104, 2025). "Gene groups linked to efferocytosis, including Tyro3, Axl, MerTK, Gas6, BAI-1, CX3CL1, CD31, CD47, Rac1, and the TIM family, represent significant targets for prospective cancer therapies." (PMID 39911848, 2025). "AXL, a member of the TAM kinase family and a receptor for growth arrest-specific protein 6 (GAS6), is known to contribute to invasion, inhibition of apoptosis, increased proliferation, and chemoresistance in various cancers." (PMID 41511287, 2025). "Spatial localization of GAS6 and GAS7 expressions within the GAS pathway revealed concentrated expression of these genes in regions populated by high-risk cancer cells." (PMID 41034991, 2025). "Accumulating evidence has demonstrated the oncogenic roles of EREG, MAFG and GAS6 in various cancers." (PMID 40819060, 2025). "Apart from PtdSer, the Gas6/TAM system has been associated with prolonged survival and increased proliferation of cancer cells, as well as with the regulation of cancer cells migration and invasion." (PMID 39057085, 2024). "The interplay between the GAS6/AXL axis plays a fundamental role not only in the development of cancer but also in the physiological processes of cell differentiation and proliferation, survival, aggregation, and inflammation." (PMID 38391974, 2024). "Kyung-Chan Kim and colleagues showed that curcumin effectively inhibits Axl phosphorylation upon Gas6 stimulation, leading to a significant decrease in cell viability, highlighting its potential as an anti-cancer agent targeting the Axl receptor." (PMID 38474160, 2024). "Growth-arrest-specific gene 6 (Gas6) is a secreted protein involved in the development of a variety of malignant tumors." (PMID 39451556, 2024). "GAS6 upregulation or AXL overexpression is often found in cancers with resistance to EGFR-targeted therapy and enhanced survival." (PMID 38892166, 2024). "Since the binding of GAS6 to AXL has been found to promote cancer progression and sdAb20 was predicted to interact with the GAS6 recognition site, we further evaluated the GAS6/AXL blocking capacity of sdAb20 in vitro using a competition assay." (PMID 38773967, 2024).
cancer (continued). "The interaction between TAMs on APCs and PtdSer on cancer cells through either Gas6 or Pros1 attenuates the immune response, leading to survival signals and favoring an immunosuppressive and anti-inflammatory microenvironment." (PMID 39057085, 2024). "Axl binds the high-affinity ligand growth-arrest-specific protein 6 (GAS6), which has been implicated to promote cell survival, proliferation, migration, and invasion in many cancer types." (PMID 39594573, 2024). "Several studies have revealed that Gas6, which is produced by macrophages, interacts with AXL to cause cancer to develop, and AXL has been linked to worse clinical outcomes." (PMID 38391974, 2024). "It is accepted that the Gas6/TAM pathway can promote the malignant transformation of various types of cancer cells." (PMID 37265798, 2023). "The Gas6/Axl signaling pathway promotes progression, metastasis, immune evasion, and therapeutic resistance in many cancer types." (PMID 36982920, 2023). "At present, hyperactivation of GAS6/AXL signaling is considered as one of the hallmarks in many types of multidrug‐resistant cancer cells." (PMID 38045829, 2023). "AXL and its ligand, i.e., growth arrest-specific 6 (GAS6) proteins axis is reported to promote cancer cell proliferation, survival, migration, invasion, and immune evasion." (PMID 36823234, 2023). "Recently, substantial resources have been deployed to develop broad therapies targeting Gas6/AXL in cancer." (PMID 37265798, 2023). "We have shown that ProS1 is a preferred ligand for Tyro3 over Gas6 in human cancer cells expressing both Tyro3 and Axl receptors, as well as identified Tyro3 signaling pathways that progress the cell cycle and support survival in cancer cells." (PMID 35518197, 2022). "The binding of AXL and its ligand growth arrest-specific protein 6 (GAS6) induces intracellular signaling that can affect cancer progression, metastasis and drug resistance." (PMID 36119516, 2022). "In the bone marrow niche, osteoblasts produce GAS6 that can activate AXL on the surface of nearby disseminated cancer cells." (PMID 35158733, 2022). "To further test the role of Gas6 in cancer cell regrowth in metastatic livers after gemcitabine treatment in humans, we generated precision cut liver slices (PCLS) from fresh liver biopsies from treatment naïve metastatic PDAC patients." (PMID 35022267, 2022). "Other factors that were found to induce cancer cell dormancy are bone morphogenetic proteins (BMPs), TGFβ2 and growth-arrest-specific protein 6 (GAS6), factors that are also known to regulate HSC quiescence." (PMID 36497192, 2022). "Since Gas6 has the highest affinity with AXL among the TAM family, AXL/Gas6 pathway is mainly being studied in cancer." (PMID 35311091, 2022). "The AXL/GAS6 axis is required for the activation of hepatic stellate cells (HSC) that can promote a permissive environment for cancer development by the production of extracellular matrix and inflammation." (PMID 35158733, 2022). "Neutrophil-derived Gas6 then activates the receptor tyrosine kinase AXL on metastatic cancer cells and promotes metastatic growth in the liver." (PMID 35022267, 2022). "We found that Gas6 secretion from neutrophils promotes cancer cell regrowth, in fact, the addition of a neutralising Gas6 antibody abolished the promitogenic effect of neutrophils." (PMID 35022267, 2022). "The high expressions of Gas6 and MFGE8 were associated with the high ESTIMATE score and stromal score in certain types of cancers." (PMID 36059952, 2022). "Gas6 is secreted by both cancer and stromal cells, and studies demonstrate that Axl is also expressed by cancer and stromal cells." (PMID 34576116, 2021). "This review examines the current state of therapeutics targeting the Gas6/Axl pathway in cancer and discusses Gas6- and Axl-targeting agents that have been evaluated preclinically and clinically." (PMID 34576116, 2021).
cancer (continued). "The result showed TAMs would receive activated signals from cancer cells through GAS6-AXL, RPS19-C5AR1, FAM3C-LAMP1, CD47-SIRPA, and VEGFA-NRP1/NRP2 L–R pairs in TME." (PMID 34676217, 2021). "In cancer cells, GAS6-activated AXL induces multiple actin-dependent cytoskeletal rearrangements that jointly contribute to invasion." (PMID 34310342, 2021). "Both molecules, the receptor, and its ligand GAS6, are commonly expressed in cancer cells, as well as stromal and infiltrating immune cells." (PMID 34638349, 2021). "Gas6 and Axl has been shown to promote growth and therapy resistance among different types of cancer." (PMID 34836355, 2021). "The Gas6/Axl signaling pathway has gained significant attention as a therapeutic target due to its implications in cancer progression, metastasis, and therapeutic resistance." (PMID 34576116, 2021). "High levels of Gas6 have been detected within the TME of various cancer types, including lung, gastric, pancreatic cancer and hepatocellular carcinoma." (PMID 35127700, 2021). "It has been shown that GAS6, released by stromal cells, activates AXL and its molecular targets in cancer cells and causes alterations in E-cadherin expression." (PMID 33182542, 2020). "This would explain why in many cancer contexts, despite the capture of GAS6 by sAXL, the activation of the receptor is still dysregulated." (PMID 33182542, 2020). "In sum these data suggest that stromal GAS6 is involved in early changes that promote the switch from preinvasive to invasive cancer." (PMID 32148495, 2020). "Gas6 is a multifunctional protein that can be secreted by several cell types and regulates multiple processes, including cancer cell plasticity, angiogenesis, and immune cell functions." (PMID 32174917, 2020). "The results of Boyden chamber assays showed that cancer cell migration was induced by GAS6 and HGF in SKOV3 cells in serum-free medium." (PMID 32055714, 2020). "Given that Gas6 and Axl are expressed on both neoplastic and host cells, targeting this pathway presents a novel strategy to impair multiple stages of cancer development, progression, and metastasis." (PMID 32660000, 2020). "The network surrounding Il10ra shows that many of them are cancer related, e.g., Reg3g, Aoc1, Mep1a, Irf7, Gas6, B3gnt7, Tap1, Tgm2, and Nos2." (PMID 33396408, 2020). "Our results revealed that GAS6 and HGF had an additive effect on cell migration, suggesting that cancer progression is promoted by various humoral factors such as GAS6 and HGF in the TME." (PMID 32055714, 2020). "Growth arrest-specific 6 (GAS6) and hepatocyte growth factor (HGF), the natural ligands of AXL and MET, respectively, are associated with the induction of cancer cell proliferation or metastasis." (PMID 32055714, 2020). "The GAS6/MER signaling pathway has emerged as a therapeutic target for human cancer and immune disorders." (PMID 32042425, 2020). "Blocking Gas6-Axl signaling inhibits cancer progression and several Axl inhibitors and warfarin (a vitamin K antagonist that blocks Gas6 signaling) are currently being tested in cancer patients, including PDA patients." (PMID 32174917, 2020). "For example, growth arrest-specific protein 6 (GAS6) has been shown to induce dormancy in several kinds of cancer cells that infiltrate the bone marrow." (PMID 32300189, 2020). "The role of the Gas6/Axl signaling pathway in cancers has been described in the “TAM receptors” section." (PMID 32370748, 2020). "In this study, we found that Gas6 and Axl expression was significantly higher in pathological carcinoma tissues from human EC patients than in adjacent normal tissues." (PMID 32432570, 2020). "There were quite a little studies confirmed that up-regulation of GAS6 will disturb those pathways and lead to incontrollable growth of body cell and finally lead to cancer." (PMID 31028135, 2019). "Consistent with prior reports in other cancer models, we found that macrophages represent the main source of Gas6 in lung tumor models." (PMID 31903163, 2019).
cancer (continued). "In this study, we have identified the ProS1-Tyro3-Erk axis as a signal transduction pathway in human cancer cells distinct from the previously reported Gas6-Axl-Akt axis." (PMID 31766614, 2019). "Gas6 is also concomitantly overexpressed in human cancers, implying that, besides receptor overexpression, TAM participate in autocrine circuits by overexpressing both receptors and ligands." (PMID 31247991, 2019). "Numerous studies have shown that upregulation of Gas6/TAM can promote development of multiple types of cancer, including lung and gastric cancer." (PMID 30700007, 2019). "Our data show that ProS1 is an active and functional ligand for Tyro3 in human cancer cells, rapidly stimulating its phosphorylation as well as Erk, moreover, predominating over Gas6 as a ligand for this specific RTK." (PMID 31766614, 2019). "Deregulated oncogenic activity of the AXL receptor tyrosine kinase (AXL) and elevated levels of its ligand GAS6 (growth arrest specific gene 6) are found in numerous types of human cancer and are directly correlated with diverse aspects of cancer pathogenesis." (PMID 31171001, 2019). "Gas6 is a vitamin K-dependent protein that is an interesting target in biomedicine due to its role in inflammation, hemostasis, and cancer (Bellido-Martín and de Frutos, 2008)." (PMID 31263416, 2019). "We also observed the same protective effects of ProS1 and Gas6 on viability of both cancer cells lines using an alternative apoptosis-inducing agent, cisplatin." (PMID 31766614, 2019). "Here, we have focused on the specific role of Tyro3 expression and activation in cancers and attempted to delineate the downstream signalling pathways activated by ProS1-Tyro3 as compared to Gas6-Axl." (PMID 31766614, 2019). "GAS6/AXL signalling functions as an important pathway driving cancer cell survival, proliferation, migration and invasion, which makes AXL a potential target in cancer treatment." (PMID 31684958, 2019). "Numerous studies have shown that upregulation of Gas6/TAM can promote the development of several cancers." (PMID 29386018, 2018). "Research concerning the role of Gas6 in different cancers has indicated that Gas6/TAM induces cancer cell proliferation." (PMID 29386018, 2018). "Upregulation of Gas6/TAM and their role in promoting cancer cell survival, proliferation and migration in numerous types of cancers suggest Gas6/TAM therapeutic targets." (PMID 29386018, 2018). "Upregulation of Gas6/TAM and their role in promoting cancer cell survival, proliferation and migration in numerous types of cancers suggests potential Gas6/TAM therapeutic targets." (PMID 29386018, 2018). "Significantly, Gas6 regulates proliferation, survival and migration of cancer cells by binding to TAM receptors." (PMID 29386018, 2018). "Gas6 binds to Axl and induces cell survival, proliferation and migration, and overexpression of Axl promotes the development of various types of cancers." (PMID 29386018, 2018). "Microenvironmental factors like BMPs and growth arrest-specific 6 (GAS6) derived from mesenchymal cells and osteoclasts, respectively, can curb proliferation and induce dormancy in cancer cells." (PMID 29616190, 2018). "In this framework, and based on the overall literature herein presented, we would like to reinforce the potential therapeutic use of Gas6/TAM signaling inhibition for cancer therapy." (PMID 29386018, 2018). "Within the context of cancer, many studies have described the involvement of Gas6/TAM in the survival, proliferation and migration of a wide variety of cancer cells." (PMID 29386018, 2018). "In this review, we will introduce the basic knowledge on Gas6 and the critical effects of Gas6 on cancer, and we will provide future directions and unresolved questions regarding Gas6." (PMID 28333143, 2017). "Gas6/TAM has a significant role in the development of numerous cancer types, highlighting Gas6/TAM as attractive targets for therapeutic development." (PMID 28333143, 2017).
cancer (continued). "The finding that Gas6 requires γ-carboxylation and PS binding for biological activity has important implications in cancer biology." (PMID 29176978, 2017). "In conclusion, self‐sustenance in cancer cells is based on a signaling synergy, individually balanced between GAS6 TAM‐dependent PDK‐RSK‐mTOR survival pathway and the AXLY779/EGFR/MET‐driven SRC‐mTOR pathway." (PMID 28675785, 2017). "In summary, numerous studies have shown that Gas6 promote development of cancers from different systems, and targeting Gas6 therapy in the future can be more feasible." (PMID 28333143, 2017). "Concerning these significant effects of Gas6 in numerous cancers, we discuss the roles of Gas6 in cancer development in this review." (PMID 28333143, 2017). "Taken together, these studies support the further development of extracellular Gas6/TAM Ig1 inhibitors as anti-cancer therapeutics." (PMID 28272423, 2017). "Acute myelocytic leukaemia (AML) is a Gas6-dependent cancer, and Gas6 expression predicts poor prognosis in AML." (PMID 28333143, 2017). "The relevance of this pathway to cancer is of potential interest given overexpression of both Ggcx and Vkorc1 have been observed in several cancers, including both liver cancer and several adenocarcinoma’s that co-express Gas6 (Oncomine database)." (PMID 27916840, 2016). "There are several potential candidate proteins containing cbEGF-like domains that participate in cancer metastasis, such as latent transforming growth factor-β (TGFβ) binding proteins (LTBPs), growth arrest specific 6 (GAS6) and CD97." (PMID 26954680, 2016). "In this review we will highlight recent literature describing the role of GAS6/AXL signaling in cancer progression." (PMID 27834845, 2016). "Recent studies suggest that GAS6 and Mer receptor signaling regulate the cell cycle status of cells as well as the induction of a stem cell phenotype in normal and cancer cells." (PMID 27028863, 2016). "Collectively, these studies suggest that GAS6 expression regulates Mer receptor signaling in both normal prostate epithelial cells and cancer cells." (PMID 27028863, 2016). "It has been reported that Gas6 is overexpressed in different human cancers when compared with normal tissue." (PMID 26207647, 2015). "The Gas6/Axl pathway has been identified as promoting cancer cell invasion in several cancers and several mechanisms have been proposed." (PMID 26207647, 2015). "Researchers have found that Gas6 expression is increased in several different cancers, potentially a biomarker for cancer patients." (PMID 26207647, 2015). "AXL is a tyrosine kinase receptor activated by GAS6 and regulates cancer cell proliferation migration and angiogenesis." (PMID 25966280, 2015). "Expression of Gas6 and Axl is increased in various types of cancers, and Axl has also been suggested as a rational target for cancer therapy." (PMID 24409287, 2014). "This review highlights the data supporting AXL as a novel treatment candidate in a variety of cancers as well as the current status of drug development targeting the AXL/GAS6 axis and future perspectives in this emerging field." (PMID 25337673, 2014). "Gas6 is secreted or expressed by various cancer cells, smooth muscle cells, retinal pigment epithelial cells, mesangial cells, and endothelial cells." (PMID 24409287, 2014). "Perhaps in RCC, where high Gas6 expression correlate with improved prognosis, Gas6 can be protective and retard cancer progression by mechanisms, such as decreased migratory potential and decreased viability." (PMID 19888345, 2009). "So far, in most human cancers where the biology of Gas6 and Axl has been studied, Axl is believed to exert oncogenic effects, and a combined increase of Gas6 and Axl expression correlate with poorer prognosis." (PMID 19888345, 2009). "Adequate evidence supports the role of the Gas6/Axl system in driving cell growth and survival in normal and cancer cells." (PMID 19888345, 2009).